BECN1 (beclin 1)
Diseases named in the same sentence as BECN1 in open-access papers (continued):
Sharing a sentence is not in itself a finding about the gene and the disease.
bacterial infection (9 papers, 2016 to 2024). "In addition, some NLRs such as NLRC4 and NLRP4 were shown to associate with Beclin 1, which in turn negatively regulates autophagy during bacterial infection." (PMID 30488027, 2018). "Especially, presence of bacterial infection was barely detected in the latter two groups, suggesting a stronger bactericidal activity in response to Beclin-1 activation." (PMID 34211859, 2021). "SR-BI was a key driver of beclin-1-dependent autophagy during acute bacterial infection of the liver and spleen." (PMID 27694929, 2016). "Although possible or definite involvement of Bcl-2 and/or the Bcl-xL-Beclin 1 complex in starvation-induced autophagy and endocytic process has been demonstrated, its precise roles in internalization and autophagy during bacterial infection remain unclear." (PMID 28085926, 2017). "Studies with the intracellular pathogen Coxiella burnetti have demonstrated that this pathogen may modulate autophagy as well as apoptosis pathways through BECN1/BCL2 interplay modification to generate a persistent bacterial infection in the host cells." (PMID 28056107, 2017). "However, the involvement of the NLRX1–Beclin 1 complex in autophagy in response to bacterial infection remains unknown." (PMID 30488027, 2018). "In addition, the direct participation of Beclin 1 in the regulation of autophagy and endocytosis-mediated internalization during bacterial infection has not been elucidated." (PMID 28085926, 2017). "Therefore, Beclin 1 may use distinct Beclin 1 complexes depending on intra- and extracellular environmental changes such as starvation and bacterial infection and Beclin 1-UVRAG but not Beclin 1-Atg14 functions in the internalization process of GAS." (PMID 28085926, 2017).
adenocarcinoma (6 papers, 2013 to 2023). A common cancer characterized by the presence of malignant glandular cells. "Well-moderately adenocarcinoma had a higher Beclin 1 expression than the poorly-differentiated subtype (P=0.0004)." (PMID 33425768, 2020). "By contrast, Beclin-1 was detected in 44% (35/80) of SCCs and 42% (10/24) of adenocarcinomas." (PMID 25202355, 2014). "In the TMA, Atg7 expression was found to be significantly upregulated (p < 0.01), whereas Beclin-1 expression was significantly decreased in adenocarcinomas compared to (not matched) normal mucosa (p < 0.001)." (PMID 32046105, 2020).
colorectal (5 papers, 2014 to 2024). "In conclusion, synbiotics supplementation might reduce protein expression of muscle protein degradation biomarkers such as beclin-1 in rats with chronic ethanol feeding, which is speculated to be linked to the improvement of intestinal tight junction and the reduction of liver damage." (PMID 34830430, 2021). "Since cytoplasmic Beclin 1 is fundamentally important in autophagy, it is conceivable that nuclear Beclin 1 plays an autophagy-independent role in colorectal tumorigenesis." (PMID 36230664, 2022). "The roles of Beclin 1 in colorectal carcinogenesis and its subsequent progression are still unclear." (PMID 25196438, 2014).
nephropathy (5 papers, 2019 to 2024). A nonspecific term referring to disease or damage of the kidneys. "Although the precise role of autophagy in kidney disease remains controversial, patients with AKI tend to exhibit reduced levels of Beclin-1 (BEC1), a representative autophagy biomarker." (PMID 37270567, 2023).
neurological diseases (5 papers, 2019 to 2025). "Previous studies have shown that VCP can stabilize Beclin 1 in neurological diseases and promote the progression of autophagy." (PMID 37269429, 2023).
benign tumors (4 papers, 2014 to 2021). "Some studies suggest the role of autophagy proteins, Beclin 1 and LC3B, in the cardioprotection of the ischemic heart." (PMID 33020418, 2020).
cardiovascular diseases (3 papers, 2017 to 2020). "BECN1 was identified as a direct target of miR-216a, implying that miR-216a controls OS induced autophagy in HUVECs by regulating intracellular levels of BECN1 and may have a relevant role in aging-associated cardiovascular disorders." (PMID 28593022, 2017).
heart disorder (3 papers, 2021 to 2023). A disease involving the heart and/or pericardium. "BECN1 is aberrantly expressed or posttranslationally modified in many heart diseases, including ischemia/reperfusion, myocardial infarction, cardiac hypertrophy, and heart failure." (PMID 34336092, 2021). "BECN1 deregulation leads to heart disease development through altered myocardial autophagy and apoptosis." (PMID 34336092, 2021).
infectious disease (3 papers, 2014 to 2024). A disorder directly resulting from the presence and activity of a microbial, viral, or parasitic agent in humans. "Multiple lines of evidence have linked altered expression of beclin 1 to several major human diseases such as cancer, infectious diseases and neurodegenerative disorders." (PMID 25275521, 2014).
hematologic malignancy (2 papers, 2022 to 2023). "We have recently reported the generation of an OVV armed with therapeutic genes such as miR-34a, Smac, and Beclin-1, which showed enhanced antitumor efficacy in hematologic malignancy." (PMID 35228544, 2022).
inflammation (2 papers, 2015 to 2022). Aberrant reaction of the microcirculation characterized by movement of fluid and leukocytes from the blood into extravascular tissues. "Mice having a defect in Beclin-1 (Beclin-1+/−), thus resulting in reduced autophagosome formation, exhibit exacerbated lung inflammation upon RSV infection, with increased Th2 responses and decreased IL-17 and IFN-γ responses." (PMID 26441964, 2015).
myopathies (2 papers, 2016 to 2022). "Seven adult patients affected by COL6 myopathies underwent a controlled low-protein diet for 12 mo and we evaluated the presence of autophagosomes and the mRNA and protein levels for BECN1/Beclin 1 and MAP1LC3B/LC3B in muscle biopsies and blood leukocytes." (PMID 27656840, 2016).
neurodevelopmental disorder (2 papers, 2023 to 2025). A behavioral and cognitive disorder with onset during the developmental period that involves impaired or aberrant development of intellectual, motor, or social functions. "Data analysis also indicates that elevated levels of tau protein, amyloid peptides and beclin 1 in the blood are a predictors of future neurodevelopmental disorders." (PMID 37686098, 2023).
blood cancer (1 paper, 2025). "As autophagy seems to play an important role in this aggressive blood cancer, it would be interesting to test/develop therapeutics to target this process, for instance nano-targeting and/or modulation of key autophagy and apoptosis components (such as beclin-1 and Bcl-2) in M1 macrophages." (PMID 41415285, 2025).
peripheral neuropathy (1 paper, 2025). A disorder affecting the peripheral nervous system. "We found that Becn1 cKO mice develop a severe recessive, and progressive dysmyelinating peripheral neuropathy, characterized by extensive involuntary tremors, motor and sensory impairments, late paresis of posterior legs, massive muscle atrophy, and body weight loss." (PMID 39680476, 2025).
BECN1 also shares sentences with these, for which no sentence is quoted: metabolic disorders (5 papers); idiopathic pulmonary fibrosis (4); Myocardial fibrosis (4); Parkinson’s (4); diffuse large B-cell lymphoma (3); endometrial adenocarcinoma (3); enteritis (3); hyperlipidemia (3); infarction (3); liver (3); retinal ischemia (3); sarcopenia (3); synovial sarcoma (3); acute leukemia (2); cholestasis (2); chronic lymphocytic (2); chronic obstructive pulmonary disease (2); Crohn disease (2); dysplastic nevi (2); E. coli infection (2); Ewing sarcoma (2); experimental autoimmune encephalomyelitis (2); fibrosarcoma (2); Hereditary breast cancer (2); hypertrophy (2); Machado-Joseph disease (2); mast cell tumors (2); muscular dystrophy (2); papillary thyroid cancer (2); prostate adenocarcinoma (2).
A further 118 diseases each share a sentence with BECN1 in 2 papers or fewer.